CEP83 (centrosomal protein 83)
Description:
Component of the distal appendage region of the centriole involved in the initiation of primary cilium assembly. May collaborate with IFT20 in the trafficking of ciliary membrane proteins from the Golgi complex to the cilium during the initiation of primary cilium assembly.
Synonyms: CCDC41; NY-REN-58; NPHP18
Tractability: PROTAC: ubiquitination databases record sites on it.
Gene: Protein-coding gene on chromosome 12 (94,306,449 to 94,459,988, reverse strand). Ensembl gene ENSG00000173588.
Subcellular location: Cytoplasm, cytoskeleton, microtubule organizing center, centrosome, centriole
Subcellular location (Human Protein Atlas): Golgi apparatus; Primary cilium; Primary cilium transition zone; Vesicles
Pathways (Reactome):
Organelle biogenesis and maintenance: Anchoring of the basal body to the plasma membrane
Gene Ontology:
Molecular function: protein binding
Biological process: cilium assembly; protein localization to centrosome; establishment of centrosome localization
Cellular component: centriole; ciliary transition fiber; Golgi apparatus; centrosome; cytosol
Genetic constraint (gnomAD): Loss-of-function variants: 28 observed, 47.56 expected, observed/expected ratio (o/e) 0.59, 90% interval 0.44 to 0.81. The upper end of that interval is the gene's LOEUF score, 0.81, which puts it in group 3 of 6, group 1 being the genes least tolerant of losing a copy. Missense variants: 357 observed, 413.82 expected, observed/expected ratio (o/e) 0.86, 90% interval 0.79 to 0.94. Synonymous variants: 118 observed, 145.8 expected, observed/expected ratio (o/e) 0.81, 90% interval 0.7 to 0.94.
Homologues: Orthologues: chimpanzee CEP83 (99% identical), macaque CEP83 (98% identical), dog CEP83 (90% identical), pig CEP83 (87% identical), rabbit CEP83 (86% identical), rat AABR07039307.1 (85% identical), guinea pig CEP83 (83% identical), mouse Cep83 (83% identical), rat Cep83 (80% identical), tropical clawed frog cep83 (59% identical), zebrafish cep83 (55% identical). Paralogues in human: LRRC45 (17% identical).
Diseases named in the same sentence as CEP83 in open-access papers:
CEP83 is named in the same sentence as 12 diseases in open-access papers, as found by Europe PMC text mining. Sharing a sentence is not in itself a finding about the gene and the disease. The quoted sentences say what the papers report.
ciliopathies (5 papers, 2015 to 2024). "Among 8 probands, we identified 12 variants in 7 genes associated with ciliopathies including Joubert syndrome (KIAA0586, ARMC4, BBS1, CEP83, ARMC9, TOGARAM1, WDR5)." (PMID 38585811, 2024). "Mutations in three genes encoding DAP proteins, namely, CEP83, CEP164, and SCLT1, have been reported to be linked to heritable ciliopathies, such as NPHP and Joubert syndromes." (PMID 34830133, 2021). "This high-confidence list includes many established ciliopathy genes such as TTC26, CEP83, IFT88, and SPATA7, as well as 14 of 25 known JS causative genes." (PMID 26026149, 2015). "Mutations in other ciliopathic genes which were not in our NGS ciliopathy panel (e.g. DZIP1L, CEP83, or many other genes that are gradually described in literature as causing ciliopathies) could cause the phenotype of cystic kidney disease in unresolved patients." (PMID 32574212, 2020).
nephronophthisis (3 papers, 2022). Progressive tubulointerstitial injury, inherited in an autosomal recessive pattern, caused by mutations in genes involved in ciliary function, which may result in an end stage renal failure. "As a protein-coding gene, CEP83 was reported to be associated with nephronophthisis, and we found it was related to NAC response for the first time." (PMID 36406127, 2022). "Although CEP83 is primarily associated with nephronophthisis, there have been two publications showing four patients who had autosomal recessive RP (arRP) without nephronophthisis." (PMID 36672815, 2022).
intellectual disabilities (1 paper, 2021). "It was shown recently that the mother centriole in aRG contains distal appendages that anchor it to the apical membrane and that CEP83 (centrosomal protein 83), a protein implicated in intellectual disabilities, is required for their maintenance." (PMID 35069108, 2021).
megalencephaly (1 paper, 2021). A congenital abnormality in which the occipitofrontal circumference is greater than two standard deviations above the mean for a given age. "Interestingly, mutations in some centrosomal/ciliary genes (e.g., Cep83, IFT88) can also lead to megalencephaly, i.e., larger brains." (PMID 34744618, 2021).
orofaciodigital syndrome IX (1 paper, 2020). "These include CEP83 (mutations in CEP83 cause NPHP18), CEP89, SCLT1 (variants in SCLT1 may be associated with Orofaciodigital syndrome 9), and FBF1." (PMID 31990917, 2020).
renal agenesis (1 paper, 2022). Renal agenesis (RA) is a form of renal tract malformation characterized by the complete absence of development of one or both kidneys (unilateral RA or bilateral RA respectively), accompanied by absent ureter(s). "It will be interesting to await future reports of additional CEP83 mutations in humans and whether complete loss of function alleles will result in broader mesoderm defects or renal agenesis." (PMID 36222666, 2022).
genetic diseases (1 paper, 2022). "Our findings are relevant to understanding the cellular and molecular functions of CEP83 and might be relevant to the pathophysiology of human genetic diseases." (PMID 36222666, 2022).
tumours (1 paper, 2021). "Likewise, the following marker genes were selected for analysis in PF tumours: LAMA2, ALDH1L1, SLC6A13, IGSF1, and CXorf67 for PFA; and NELL2, DNAH1, CEP83, C9orf72, and NXNL2 for PFB tumours." (PMID 34314101, 2021).
CEP83 also shares sentences with these, for which no sentence is quoted: Joubert syndrome (2 papers); alopecia (1); cystic kidney disease (1); Retinal dystrophy (1).